CD34 (CD34 molecule)
Diseases named in the same sentence as CD34 in open-access papers (continued):
Sharing a sentence is not in itself a finding about the gene and the disease.
melanoma (continued). "Other pertinent negative immunostains include hematolymphoid markers (CD45, CD3, CD20, CD79a), myoid markers (smooth muscle actin (SMA), desmin), vascular markers (CD31, CD34), epithelial markers (EMA, keratins), melanoma markers (melanA, SOX10, HMB45, S100), and other markers (ALK, CD30)." (PMID 40563703, 2025). "The N5 subset (CD10-CD16+CD34-), a non-proliferative immature population with low phagocytic activity, was markedly expanded in melanoma patients, potentially reflecting “emergency granulopoiesis”." (PMID 41451221, 2025). "Immunohistochemically, the tumor cells were positive for S100 (5/6), cyclin D1 (2/3), SATB2 (2/3), BCOR (2/4), and TLE1 (1/3) while negative for MUC4 (0/6), keratin (0/5), EMA (0/4), desmin (0/6), CD34 (0/6), SMA (0/5), SOX10 (0/5), and melanoma cocktail (0/2)." (PMID 40705064, 2025). "Spindle-shaped cells infiltrate the dermis in desmoplastic melanoma, but unlike in nephrogenic systemic fibrosis, these cells do not express CD34." (PMID 39188505, 2024). "The negative reactivity of tumor cells for other lineage-specific markers, such as cytokeratin AE1/AE3, S100 protein, CD34, and SMA/desmin, allows distinction from poorly differentiated squamous cell carcinoma, melanoma, angiosarcoma, and leiomyosarcoma, respectively." (PMID 39449379, 2024). "CUPS is typically positive for CD10, vimentin, CD68 and actin, whilst it is negative for pancytokeratins, CD34, melanoma markers melanA, S100 protein and HMB45." (PMID 37238306, 2023). "Lastly, evaluation for RNA levels of TYR, CD34, and CALD may help to further differentiate between canine oral amelanotic spindloid malignant melanomas and oral soft tissue spindle cell sarcomas." (PMID 35448673, 2022). "Finally, immunofluorescence staining of human melanoma tissues revealed that in addition to tumour cells, ATF4 is highly expressed in CAFs (αSMA) that localized to the perivascular area (CD34)." (PMID 35654839, 2022). "p32 silenced B16F10 cells subcutaneous tumors showed decreased proliferation (Ki-67), angiogenesis (CD34), leukocyte (CD45), macrophage (F4/80) markers, and vimentin expression than control tumors confirming its involvement with p32-mediated melanoma tumor progression." (PMID 34711805, 2021). "Using a mouse model of spontaneous melanoma, we showed that CD34− but not CD34+ tumor-initiating cells (TICs) depend on M2 macrophages for survival and proliferation." (PMID 25294815, 2014). "A clinical trial conducted by Banchereau and colleagues for similarly advanced-stage melanoma patients using bulk CD34+ HPC-derived DCs, which included LCs, pulsed with a mixture of melanoma-derived peptides, resulted in durable immune responses associated with long-term survival." (PMID 23837662, 2013). "Immunohistochemistry stains were positive for desmin, smooth muscle actin (SMA), CD34 and negative for human melanoma black (HMB)-45 antigen and CD117." (PMID 27785206, 2012). "Both melanoma and normal skin-derived cell populations express the fibroblastic marker FSP-1 (Fibroblast Specific Protein-1) and the mesenchymal marker vimentin, but not the epithelial marker E-cadherin, the endothelial marker CD31, the hematopoietic marker CD34 or the leukocyte marker CD45." (PMID 28423623, 2017). "However, staining was negative for CD34, desmin, S-100 protein, cytokeratin, human melanoma black (HMB)-45, B-cell lymphoma (Bcl)-2 and CD99." (PMID 24348865, 2014). "However, the tumor cells were negative for NFP (neurofilament protein), CD34, desmin, actin, chromogranin, synaptophysin, and pan-melanoma." (PMID 23320233, 2012). "Notably, CD34 expression is generally absent in melanocytic tumor samples and in the current studies, we found no significant CD34 staining on murine melanoma cells." (PMID 21494591, 2011). "CD34+ cells were co-cultured with or without melanoma cells using Transwell dishes." (PMID 11747338, 2001).
melanoma (continued). "Melanoma CTCs must express CD146 and HMW-MAA receptors but not the leukocyte and endothelial cell markers (CD45 and CD34) to be considered CTCs." (PMID 37446253, 2023). "We then used our lentiviral vector containing the melanoma-reactive TIL1383I TCR and a non-signaling truncated CD34 transduction marker to transduce T cells, generating TIL1383I TCR-modified T cells." (PMID 34172810, 2021). "Case two exhibited a negative result for the expression of GIST markers CD34 and CD117, while case four exhibited a negative result for thyroid transcription factor and the melanoma marker HMB45." (PMID 25435998, 2015). "The immunohistochemical analysis of the EGD biopsy showed that the tumor was immunoreactive with CD117, CD34 and DOG1 while markers of carcinoma, melanoma and lymphoma were negative." (PMID 25185706, 2014). "Multiple endoscopic biopsies were obtained which showed that the tumor was immunoreactive with CD117, CD34 and DOG1 while markers of carcinoma, melanoma and lymphoma were negative." (PMID 25185706, 2014). "Further immunohistochemistry revealed a weak positive staining for CD74, the HLA-DR associated invariant chain, negative staining for cytokeratins, the melanoma antigen HMB45 and CD34." (PMID 23880011, 2013). "To assess the function of CD34 on hematopoietic and non-hematopoietic cells we implanted B16F1 melanoma cells into wildtype and Cd34−/− mice, as well as bone marrow-reconstituted chimeras." (PMID 21494591, 2011). "All other markers tested were negative (pan-melanoma, HMB45, Melan A, keratin AE1/AE3, desmin, alpha smooth muscle actin, h-caldesmon, CD34, p16, CD117, DOG1, myogenin, CD10, estrogen receptor (ER), progesterone receptor (PR), PAX8, WT1, synaptophysin, chromogranin A, CD99 and PRAME))." (PMID 39196362, 2024). "The CellSearch melanoma kit identifies MCAM/MCSP double positive, CD45/CD34 negative cells as CTCs." (PMID 24915896, 2014). "However, histological findings showed an undifferentiated neoplasm and none of the immunohistochemical stains for melanoma, including S100, HMB-45, Melan A, tyrosinase, CK, CD-34, c-Kit and LCA were able to clarify its origin." (PMID 18445301, 2008).
myelodysplastic syndrome (93 papers, 2008 to 2025). A clonal hematopoietic disorder characterized by dysplasia and ineffective hematopoiesis in one or more of the hematopoietic cell lines. "MiR-210 level is increased in CD34+ cells in myelodysplastic syndromes, a disease caused by abnormal proliferation and differentiation of hematopoietic stem cells." (PMID 28977934, 2017). "A comprehensive RNA-seq analysis of CD34 + cells from patients with myelodysplastic syndromes (MDS) harboring these SFs mutations revealed > 200 disrupted splicing events for each mutated SF and over 100 genes were found to be aberrantly spliced." (PMID 39528914, 2024). "Ribosomal protein (RP) L23 is a negative regulator of cellular apoptosis, and RPL23 overexpression is associated with abnormal apoptotic resistance in CD34+ cells derived from patients with higher-risk myelodysplastic syndrome (MDS)." (PMID 28539603, 2017). "The selected dataset explored the molecular basis of myelodysplastic syndromes with a deletion of the long arm of chromosome 5, del(5q), by analyzing the transcriptional and regulatory landscape of CD34 + progenitor cells using single-cell RNA-seq." (PMID 40841877, 2025). "In CD34 + cells from myelodysplastic syndrome (MDS) patients, there is increased methylation of rDNA promoters, leading to reduced expression of rRNA and disruption of ribosomal biogenesis compared to healthy controls." (PMID 39085958, 2024). "For example, Medyouf and colleagues found that the addition of patient-derived mesenchymal stromal cells improved engraftment of CD34+ cells from patients with Myelodysplastic syndromes after intrafemoral injection." (PMID 38145377, 2023). "Dlk1 encodes a non-canonical Notch ligand which has been reported to be overexpressed in human hematopoietic CD34+ stem and progenitors from myelodysplastic syndrome patients." (PMID 37353813, 2023). "The expression of CD34+ marker is associated with multi‐drug resistance (MDR) in AML and myelodysplastic syndrome (MDS) patients." (PMID 35128828, 2022). "For example, in higher-risk myelodysplastic syndrome (MDS) patients, studies showed that overexpression of RPL23 was associated with the abnormal apoptotic resistance in CD34+ cells." (PMID 34926291, 2021). "In the myelodysplastic syndromes (MDS), inhibition of TLR2 in cultured BM CD34+ cells from patients with lower risk MDS led to increased formation of erythroid colonies." (PMID 33711076, 2021). "We analyzed a set of CD34+ hematopoietic stem cells and myelodysplastic syndrome samples and found a set of genes whose isoform diversity change is associated with SF3B1 mutations." (PMID 34499147, 2021). "Microvesicles released from MSCs from patients with myelodysplastic syndrome (MDS) have been shown to alter CD34 + cells characteristics." (PMID 33521365, 2021). "Methylation at the rDNA promoter correlated negatively with 45S pre-rRNA abundance in hepatocellular carcinoma and CD34+ cells in patients with myelodysplastic syndrome." (PMID 32582584, 2020). "Aberrant innate immune activation plays a central role in the pathogenesis of myelodysplastic syndrome, and gene expression profiles of myelodysplastic CD34+ cells demonstrate upregulation of interferon response genes." (PMID 32841218, 2020). "For instance, by clustering the curated signatures from genetic perturbation and diseases, we found multiple myelodysplastic syndrome (MDS) signatures from CD34+ cells that cluster with ERBB2 overexpression signatures from MCF10A cells." (PMID 30594974, 2019). "Myelodysplastic syndrome (MDS) is a collection of hematopoietic malignancies in which genomic abnormalities within the CD34+ hematopoietic stem/progenitor cell (HSPC) compartment lead to ineffective hematopoiesis and morphological dysplasia of blood cells." (PMID 29925839, 2018). "In particular, they found that EV miR-7977 derived from AML/myelodysplastic syndrome (MDS) CD34+ cells, was transferred into BM MSCs and reduced their ability to support CD34+ cells." (PMID 28574430, 2017).
myelodysplastic syndrome (continued). "By quantitative polymerase chain reaction (Q-PCR), upregulation (≥twofold) of PD-L1 and PD-L2 mRNA in CD34-positive cells was observed in 36 and 12% of patients with myelodysplastic syndrome (MDS)." (PMID 28482851, 2017). "Other studies have confirmed decreased miR-146a levels in CD34+ cells of the 5q- myelodysplastic syndrome compared to the levels observed in normal CD34+ cells." (PMID 22453030, 2012). "In fact, some individual GE profiles from bone marrow CD34+ samples from myelodysplastic syndromes were very similar to normal CD34+ cells and clustered within their groups." (PMID 18698424, 2008). "Our analysis of differentially expressed genes (DEGs) in CD34+ hematopoietic stem cells (HSCs) from patients with myelodysplastic syndromes (MDS) revealed significant differences in gene expression patterns compared to the control group (individuals without MDS)." (PMID 40073065, 2025). "Expression of JMJD3 was found up-regulated in MDS CD34+ cells in human myelodysplastic syndrome." (PMID 31701394, 2019). "The decreased expression of rRNA in CD34+ cells from patients with myelodysplastic syndromes may reduce the synthesis of ribosomal proteins leading to defective hematopoiesis and bone marrow failure." (PMID 31169368, 2019). "Hypomethylation led to the hyperactivation of rRNA gene transcription in human hepatocellular carcinomas, lung cancer, and cervical cancer, whereas hypermethylation led to the repression of rRNA gene transcription in CD34+ cells derived from patients with myelodysplastic syndromes." (PMID 31169368, 2019). "Our hypothesis was that mesenchymal stromal cells (MSC) from myelodysplastic syndrome (MDS) patients could modify CD34+ cells properties by MVs." (PMID 26836120, 2016). "Additionally, bone marrow mononuclear and CD34+ cells from individuals with myelodysplastic syndromes, express increased levels of TLR4 when compared to the constitutive expression of TLR4 in the absence of these hematological syndromes." (PMID 26555697, 2015). "In myelodysplastic syndrome (MDS), GPRC5A mRNA levels were found to be lower in CD34+ cells, which could explain these cells' susceptibility to cell damage." (PMID 25621293, 2014). "The miR-155-5p molecule plays a role in the programmed cell death of CD34 + cells in Myelodysplastic Syndromes (MDS) through the RAC1/CREB/miR-15b pathway, thereby suppressing the production of blood cells in the bone marrow." (PMID 38462628, 2024). "In particular, TLR2 is overexpressed in the neoplastic CD34+ hematopoietic stem and progenitor cells characteristic of the myelodysplastic syndromes (MDS), and its activation induces the production of IL-8 and inhibits their erythroid differentiation." (PMID 33321934, 2020). "Immunophenotypic profiles of HSPC subpopulations were examined in BM samples of 10 newly diagnosed CD34+/CD38− AML patients, 6 patients with myelodysplastic syndromes (MDS), and 7 healthy donors (HDs)." (PMID 40362463, 2025). "Recent studies have shown that in myelodysplastic syndromes (MDS), AML patients had high expression of PIM2 in CD34+ cells derived from bone marrow." (PMID 33854618, 2021). "In patients with Diamond-Blackfan anemia (DBA) and myelodysplastic syndrome (MDS), dexamethasone treatment dysregulates ribosome function and increases the number of erythroid cells produced from normal CD34(+) cells and from CD34(+) cells with the types of ribosome dysfunction." (PMID 34735568, 2021). "Various studies have revealed that some of these genetic abnormalities originate from early HSCs (CD34+CD38−CD45RA−CD90+/CD49f+), providing the strongest evidence for the existence of Myelodysplastic syndrome-initiating cells (MDS-ICs)." (PMID 34439269, 2021).
myelodysplastic syndrome (continued). "A study of immune infiltration in patients with myelodysplastic syndrome with advanced clinical pathological features found that CYBRD1 expression regulates the cell cycle and DNA repair, whereas CD34 is downregulated and triggers an immune response." (PMID 34594380, 2021). "In early stage myelodysplastic syndromes (MDS), CD34+ cells exhibitedelevated expression levels of the pro-apoptotic proteins such as Bax and Bad, whichindicate an overall apoptotic trend (Parkeret al., 2000)." (PMID 33432966, 2021). "WT1 is overexpressed in acute leukemias and myelodysplastic syndromes (MDS) and has limited expression on normal CD34+ hematopoietic stem cells." (PMID 34943884, 2021). "Notably, when co-cultured with recombinant human PD-L1, PD-1-positive CD71+ red lineage progenitor cells and PD-1-positive CD34+ hematopoietic stem progenitor cells (HSPCs) activate caspase-3 in myelodysplastic syndromes (MDS)-pre-AML lesions, resulting in apoptosis and ineffective hematopoiesis." (PMID 41451233, 2025). "Genomic loss of one HLA haplotype was first described in 2009 in patients relapsing after haplo-HCT for AML and myelodysplastic syndrome (MDS) (either non-T-cell depleted or using purified CD34+ cells with subsequent DLI)." (PMID 37951964, 2023). "On the other hand, TWIST1 is shown to enhance the expression of miR-10a in CD34+ cells in myelodysplastic syndrome, and TWIST1/miR-10a-axis could be used as a therapeutic target in the treatment of the myelodysplastic syndrome." (PMID 36555120, 2022). "Relationship between the degree of proliferation of non-lymphoid CD34+ and nucleated red blood cells from patients with myelodysplastic syndromes (MDS) and other haematological and biochemical characteristics of the disease." (PMID 22952954, 2012). "Another hematologic malignancy, myelodysplastic syndromes (MDS), has been difficult to engraft in NSG mice, but CD34+ HSPCs from MDS patients engrafted well in MISTRG mice." (PMID 37296949, 2023). "In patients with del(5q) myelodysplastic syndrome (MDS), the transcription factor FOXM1 is frequently downregulated in CD34+ cells." (PMID 37526082, 2023). "DLK1 expression is elevated in the CD34+ cells and MNCs of myelodysplastic syndrome (MDS) patients and MNCs of AML patients, and increased levels of DLK1 are found in MDS patient sera." (PMID 30876483, 2019). "Recently, overexpression of CLL1 by CD34+ CD38- bone marrow fraction and its various subcompartments (HSC, MPP and LMPP) has been demonstrated in patients with MDS-EB (myelodysplastic syndromes with excess blasts), compared to LR-MDS and healthy individuals." (PMID 34490124, 2021). "The presence of intronic ncRNA transcripts differentially expressed in CD34+ and stromal cells may shed light upon the not yet fully understood molecular mechanisms involved in the heterogeneity of myelodysplastic syndromes and suggest that ncRNAs may play a role during disease development." (PMID 20633296, 2010). "In the second cluster that we chose to highlight, multiple myelodysplastic syndrome (MDS) signatures from CD34+ cells (GSE4619, GSE19429) and ERBB2 overexpression signature from MCF10A cells (GSE14990) cluster together, suggesting that the up-regulation of ERBB2 may have a role in MDS." (PMID 27667448, 2016).